AR (androgen receptor)
Diseases named in the same sentence as AR in open-access papers (continued):
Sharing a sentence is not in itself a finding about the gene and the disease.
bladder cancer (continued). "Thus, the expression of BXDC2 was inversely correlated with the expression/activity of AR in bladder cancer cells." (PMID 33652650, 2021). "Nevertheless, the expression and androgen receptor activity are correlated with bladder cancer." (PMID 33919565, 2021). "The hypothesis for the cause of these results is that the prognosis of bladder cancer is related to AR signaling." (PMID 34552102, 2021). "Potential downstream targets of AR signals in bladder cancer cells have been explored." (PMID 34064926, 2021). "AR expression in bladder cancer has been assessed by immunohistochemistry in surgical specimens." (PMID 34064926, 2021). "We also previously showed ERK activation by androgen treatment in AR-positive bladder cancer cells." (PMID 33652650, 2021). "Additionally, in mouse xenograft models for bladder cancer, AR inactivation resulted in the retardation of tumor growth." (PMID 34064926, 2021). "These discordant findings on AR levels in various grades/stages of bladder cancer might be due to the use of different antibodies and/or protocols for staining as well as the lack of standardization in scoring." (PMID 34064926, 2021). "Thus, CDDP resistance via the AR → ERK → BXDC2 signaling pathway in bladder cancer cells was strongly suggested." (PMID 33652650, 2021). "Based on the evidence, androgens and ARs play an important role in bladder development; it is believed that blocking AR signaling may work in bladder cancer therapy." (PMID 33919565, 2021). "Thus, the expression of GULP1 was inversely related to the expression/activity of AR in bladder cancer cells." (PMID 34576193, 2021). "An inverse association between AR and GULP1 expression was seen in bladder cancer cell lines." (PMID 34576193, 2021). "Therefore, we wanted to explore the possibility of AR regulation as a target for overcoming the drug resistance of bladder cancer." (PMID 32781788, 2020). "Alternations within the AR gene have also been documented in bladder cancer." (PMID 32759680, 2020). "Furthermore, binding of AR to the CD24 promoter at an AR-responsive element in bladder cancer cells was suggested." (PMID 32759680, 2020). "Another recent study has shed light on the role of the AR in cisplatin-resistant bladder cancer." (PMID 32781788, 2020). "Androgen hormone-binding activates AR leading to the progression of bladder cancers." (PMID 32104638, 2020). "It was observed that AR inhibition by enzalutamide affected the migration of bladder cancer cells." (PMID 32781788, 2020). "As expected, the AR expression in bladder cancer cells was lower than that of prostate cells." (PMID 32781788, 2020). "Although further in-depth research is needed to validate the results of our study, our findings suggest that KDM7A could be a new target for treating bladder cancer and overcoming drug resistance, in conjunction with an AR inhibitor." (PMID 32781788, 2020). "In general, AKR1C3 expression and AR-signalling are related to the development of several malignancies (e.g., bladder cancer, renal cell carcinoma, hepatocellular cancer, and endometrial cancer), as well as ovarian, breast, and pancreatic cancers, all of which are therapeutic targets of olaparib." (PMID 33114555, 2020). "Since androgen receptor activation may play a role in urothelial tumorigenesis, we can presume that 5-ARIs would be beneficial to patients with bladder cancer." (PMID 32917158, 2020). "It is worth noting that, although the authors demonstrated that SMYD3 physically interacted with the BCLAF1 promoter, it is possible that SMYD3 may regulate bladder cancer growth via AR, because of its previously reported interaction with the receptor." (PMID 32781788, 2020). "Our finding that the protein and mRNA levels of KDM7A are increased in bladder cancer tissues may point to elevated AR activity in the cancer." (PMID 32781788, 2020).
bladder cancer (continued). "It has to be considered that AR expression, and thus the role of AR, might change during the progression of bladder cancer, as indicated by the previously cited studies." (PMID 30961575, 2019). "We indicate that AR plays an essential role in bladder cancer progression in male patients." (PMID 31119584, 2019). "The AR pathway is now attracting attention in BC research, and may provide new methods to treat bladder cancer and prevent its recurrence." (PMID 30961575, 2019). "Therefore, androgen-activated AR signaling is an attractive regulatory target for the inhibition or prevention of bladder cancer incidence in men." (PMID 31119584, 2019). "Androgen-mediated AR signaling was also described to induce EMT in bladder cancer cells." (PMID 31119584, 2019). "Androgens were shown to activate β-catenin/Wnt signaling in AR positive bladder cancer cells (BCC)." (PMID 31027362, 2019). "The aim of present study was to explain whether the progression of bladder cancer in men is dependent on androgen/AR signaling." (PMID 31119584, 2019). "Also in bladder cancer, CpdA was reported to inhibit cell proliferation and induce cell cycle arrest and apoptosis in GR+/AR+ cells, and to reduce tumor growth more strongly than Dex in a xenograft model." (PMID 29738549, 2018). "Further investigation of glucocorticoids and GR signals, as well as the functional interplay between the GR and the AR or the ERα/ERβ, in urothelial cancer may thus provide novel therapeutic options in patients with bladder cancer." (PMID 30518063, 2018). "Therefore, in the current study using a meta-analysis, we aimed to determine the expression status of AR, ERα, and ERβ immunohistochemically detected in different grades or stages of bladder cancers and its potential role as prognosticators." (PMID 28362839, 2017). "In addition to the differential expression of AR protein, genetic alterations involving the AR gene have been documented in bladder cancer." (PMID 28241422, 2017). "Subsequent studies using mouse xenograft models for bladder cancer demonstrated that orchiectomy or treatment with anti-AR compounds could considerably inhibit tumor growth." (PMID 28241422, 2017). "Androgen-mediated AR signals were also shown to induce epithelial-to-mesenchymal transition via modulating the expression of Slug and the activity of β-catenin/Wnt signaling in bladder cancer cells." (PMID 28241422, 2017). "A cross-talk between AR-co-regulators and other signaling pathways in bladder cancer cells may further promote urothelial tumorigenesis and tumor progression." (PMID 28241422, 2017). "Because the number of the studies included in the current meta-analysis for each receptor is relatively small, we may need to accumulate more data to re-evaluate the significance of AR/ERα/ERβ expression in bladder cancer outgrowth." (PMID 28362839, 2017). "Similarly, in vitro assays have demonstrated that androgen-mediated AR signals promote the migration and invasion of bladder cancer cells." (PMID 28241422, 2017). "More recently, in vitro assays demonstrated that bladder cancer cells could recruit B cells, T cells, and neutrophils, leading to the induction of cell invasion as well as the expression of AR and MMPs." (PMID 28241422, 2017). "Additionally, in the uroplakin II-SV40T transgenic model, castration reduced microvessel density in bladder tumors and increased the expression of an anti-angiogenic factor TSP-1, indicating the promotion of angiogenesis by AR activation in bladder cancer." (PMID 28241422, 2017). "Furthermore, androgen or anti-androgen treatment resulted in a decrease or an increase, respectively, in sensitivity to cisplatin in AR-positive bladder cancer cells, presumably via modulating the activity of a key factor of cisplatin resistance NF-κB." (PMID 28241422, 2017). "In addition to its involvement in urothelial carcinogenesis, there have been a variety of studies suggesting that androgens and/or AR promote bladder cancer progression." (PMID 28241422, 2017).
bladder cancer (continued). "Moreover, AR activation has been correlated with resistance to chemotherapy in bladder cancer cells." (PMID 28362839, 2017). "Lastly, further research should be carried out to determine whether ligands acting on sex hormone receptors (AR or ER) and the GR isoforms or AhR targeting can provide preventive measures against bladder cancer as these are known modifiers of the UGT isozymes." (PMID 27690298, 2017). "Androgens have also been studied to determine their role in bladder cancer progression and studies suggest they may have an impact, or at least the androgen receptor (AR)." (PMID 27690298, 2017). "Moreover, AR and β-catenin co-express at the nuclei of bladder cancer cells and form a complex with T-cell factor, a co-factor of β-catenin and a downstream component of Wnt signaling, in the presence of androgens." (PMID 28241422, 2017). "Interestingly, recent studies have shown increased Wnt/β-catenin signaling in response to AR activation in several bladder cancer cell lines." (PMID 26862755, 2016). "In this study, we aimed to investigate whether AR signals have an impact on sensitivity to CDDP in bladder cancer cells." (PMID 27322140, 2016). "We therefore investigated whether androgens/AR regulate the expression and activity of NF-κB in bladder cancer cells." (PMID 27322140, 2016). "Preclinical findings have suggested that ADT inhibits the growth of AR-positive bladder cancer." (PMID 27322140, 2016). "Targeting AR during chemotherapy may thus be a useful strategy to overcome CDDP resistance in patients with AR-positive bladder cancer." (PMID 27322140, 2016). "CpdA's selective GR actions and to a lesser extent its antagonistic AR actions also contribute to the compound's ability to inhibit bladder cancer cell proliferation, colony formation, cell migration and invasion, and to increase cell cycle arrest and apoptosis." (PMID 27713909, 2016). "Recent studies have revealed that there is a 3:1 incidence in men compared to women for bladder cancer, which may be mediated by the androgen receptor (AR)." (PMID 27036026, 2016). "Finally, we immunohistochemically stained for AR, NF-κB, and p-NF-κB in our tissue microarrays (TMAs) consisting of muscle-invasive bladder cancer specimens from patients who subsequently received neoadjuvant GC therapy." (PMID 27322140, 2016). "In bladder cancer cell lines resistant to doxorubicin, AR expression was shown to be elevated." (PMID 27322140, 2016). "In the current study, we therefore assessed whether AR activation induced resistance to CDDP treatment in bladder cancer cells." (PMID 27322140, 2016). "We aimed to identify downstream targets of androgen-mediated AR signaling in bladder cancer cells." (PMID 26342199, 2015). "Coexpression of nuclear β-catenin and AR in bladder cancer cells was also noted." (PMID 26770009, 2015). "However, the role of AR in bladder cancer and the proclivity for males has only recently drawn attention." (PMID 26347776, 2015). "Several human bladder cancer cell lines have been found to express AR." (PMID 26347776, 2015). "A continuing understanding of the roles of AR and other molecules, such as GRβ, that may directly or indirectly regulate androgens may help reveal better strategies for the management of bladder cancer in males." (PMID 26347776, 2015). "Additionally, it has been found that dihydrotestosterone upregulates ERBB2 in androgen receptor positive bladder cancer cells." (PMID 26347776, 2015). "Recently, we found that compound A, a plant derivative known to function as a GR agonist as well as an AR antagonist, induced only GR transrepression in bladder cancer cells and more efficiently inhibited tumor growth than dexamethasone or an antiandrogen flutamide." (PMID 26770009, 2015). "Additionally, AR expression has been detected in human bladder cancer obtained after surgical removal." (PMID 26347776, 2015).
bladder cancer (continued). "The glucocorticoid receptor- (GR-) α isoform has an important role in suppressing inflammatory processes, which may be attenuated by AR in the development of bladder cancer." (PMID 26347776, 2015). "ELK1 is indeed activated in bladder cancer, which is further induced by AR activation." (PMID 26342199, 2015). "We thus narrowed down the candidate to ELK1 and further investigated whether ELK1 could be activated by androgen-mediated AR signaling in bladder cancer cells and thereby affected tumor progression." (PMID 26342199, 2015). "AR signals activate Wnt/β-catenin signaling in bladder cancer cells." (PMID 26770009, 2015). "Connecting AR in prostate and bladder cancers, dysregulation of the epidermal growth factor receptor (EGFR) is associated with bladder cancer, suggesting that these cancer pathways may be interconnected." (PMID 26347776, 2015). "Thus, ELK1 and AR signals appear to require each other for their functions at least in bladder cancer cell proliferation." (PMID 26342199, 2015). "This suggests that GRβ may positively affect AR signaling activity and that chronic glucocorticoid treatment in males could result in activation of the GRβ/AR axis leading to bladder cancer." (PMID 26347776, 2015). "In the current study, we investigated whether androgen could activate ELK1, as a downstream target of AR, in bladder cancer cells as well as whether ELK1 could affect their proliferation and migration in the presence and absence of androgen." (PMID 26342199, 2015). "In addition, molecular mechanisms of how androgens activate the AR pathway in bladder cancer cells are to be further investigated." (PMID 26342199, 2015). "Treatment with N-butyl-N-(4-hydroxybutyl) nitrosamine caused the development of bladder cancer in more than 92% of wildtype male mice and 42% of wildtype female mice, whereas no AR knockout mice developed bladder cancer." (PMID 26123203, 2015). "Although accumulating preclinical evidence indicates the involvement of androgen receptor signals in bladder cancer (BC) development, its clinical relevance remains unclear." (PMID 25557268, 2014). "In addition, ASC-J9 was demonstrated to reduce AR-promoted tumor growth in liver and bladder cancer." (PMID 23599788, 2013). "Furthermore, in human transitional carcinoma AR-positive cell lines, knockdown of AR expression increased cell death and decreased proliferation and migration of bladder cancer cells." (PMID 23599788, 2013). "Indeed, the expression of major AR coactivators, including TIF2, was detected in bladder cancer cell lines as well as in AR-positive and even AR-negative bladder tumor specimens and TIF2 knockdown resulted in a decrease in androgen-mediated cell proliferation." (PMID 22922989, 2012). "The purpose of this study was to investigate the effects of EGF on AR activity in bladder cancer." (PMID 22922989, 2012). "Although detailed mechanisms need to be clarified, these results may imply that elevated levels of TIF2 contribute to EGF/androgen-enhanced AR trans-activation in bladder cancer cells." (PMID 22922989, 2012). "Similarly, in bladder cancer lines 5637-AR and J82-AR where a wild-type AR was stably overexpressed, the effect of EGF was less significant than that of DHT." (PMID 22922989, 2012). "In conclusion, EGF could increase AR transcriptional activity and cell proliferation in bladder cancer." (PMID 22922989, 2012). "Both Src and ERβ were co-immunoprecipitated with AR in bladder cancer cells." (PMID 22922989, 2012). "In the present study, we provided evidence suggesting that EGF could regulate cell proliferation by activating AR signals in bladder cancer." (PMID 22922989, 2012). "Thus, our results support the possibility that EGF mediates AR transcriptional activity through the EGFR and AR pathways in bladder cancer cells." (PMID 22922989, 2012).
bladder cancer (continued). "Thus, concurrent ADT may considerably enhance the efficacy of intravesical BCG immunotherapy particularly in men with AR-positive bladder cancer, while AR immunohistochemistry may be useful for predicting response to BCG therapy." (PMID 40486871, 2025). "Similarly, AR overexpression or knockdown/inactivation was also documented to induce or reduce, respectively, the expression of PD-L1 in bladder cancer cells where circ_0001005 and miR-200a-3p, which further enhanced the cytotoxicity of NK cells, were involved." (PMID 40486871, 2025). "However, research has demonstrated that AR and the androgen signaling pathway play a role in the etiology and progression of bladder cancer, and combining antiandrogens with BCG immunotherapy could improve its efficacy." (PMID 39410541, 2024). "Sex hormones and their corresponding receptors may play a role in the occurrence and development of bladder cancer, and the presence of the androgen receptor (AR) gene, which is situated on the X chromosome, could potentially explain the differences in bladder cancer occurrence across genders." (PMID 39682286, 2024). "Therefore, it is possible that both androgen levels and AR expression may have a tumor-promoting effect in bladder cancer, and both potentially contribute to the observed disparities in incidence between male-sex and female-sex." (PMID 37666817, 2023). "AR signaling could enhance the proliferation and motility of bladder cancer cells in vitro." (PMID 35053220, 2022). "Underlying mechanisms for resistance to cisplatin-based chemotherapy in bladder cancer patients are largely unknown, although androgen receptor (AR) activity, as well as extracellular signal-regulated kinase (ERK) signaling, has been indicated to correlate with chemosensitivity." (PMID 33652650, 2021). "Moreover, activation of the androgen receptor and estrogen receptor pathways has been implicated in modulating sensitivity to conventional non-surgical therapy for bladder cancer." (PMID 34064926, 2021). "Considering the omnipresence of BPA in urine and its impact as an endocrine disruptor through ERs and the AR, we hypothesized that BPA would impact the metabolism of healthy and cancer-associated bladder fibroblasts, which could promote bladder cancer progression." (PMID 34771623, 2021). "In addition, the expression status of GULP1, along with that of AR, may serve as a predictor of chemosensitivity in patients with bladder cancer." (PMID 34576193, 2021). "As, in this study, we revealed 22% of SCCs and 16% of AC/UrCs AR-positive, anti-AR therapy might address a significant proportion of patients, and we are looking forward to future clinical trials also including aberrant differentiated bladder cancers." (PMID 34768978, 2021). "Additionally, DHT-mediated activation of Akt is AR dependent in bladder cancer." (PMID 31119584, 2019). "However, the role of AR in bladder cancer remains unclear and further characterization is still necessary." (PMID 31253132, 2019). "Thus, androgen-mediated AR signals appear to synergize with β-catenin in bladder cancer cells and may thereby promote tumor growth." (PMID 28241422, 2017). "Targeting of AR, ERβ or GRβ may provide a novel treatment for bladder cancer." (PMID 27690298, 2017). "Meanwhile, although no somatic mutations in the AR gene were found in 99 cases of bladder cancer, a molecular profiling data search identified them in up to 4% (2 of 50) of urothelial carcinomas of the bladder as well as in 6.1% (2 of 33) of plasmacytoid urothelial carcinomas." (PMID 28241422, 2017). "Importantly, enzalutamide was found to inhibit AR-positive bladder cancer xenograft growth in vivo." (PMID 28085048, 2017).